BRCA1 (BRCA1 DNA repair associated)
Diseases named in the same sentence as BRCA1 in open-access papers (continued):
Sharing a sentence is not in itself a finding about the gene and the disease.
tumor (continued). "Among them, cell cycle inhibitors, including Smads and CDKNs, were down-regulated while CDKs, CCNs, E2Fs ATM, ATR, ERCC6, MCMs, and BRCA1 were up-regulated, consistent with a tumor-promoting effect." (PMID 39759123, 2025). "In the setting of early-stage, T1N0 disease, we found that 79% of BRCA1 carriers still underwent chemotherapy, largely due to more aggressive tumor biology with TNBC." (PMID 40275390, 2025). "Alterations or overexpression of BRCA1 in OC cells can significantly drive tumor progression, especially under genotoxic stressors like radiation." (PMID 41186627, 2025). "Early models designed LNPs with tumor-specific uptake in BRCA1+ patients by correlating lipid pKa (5.1–6.9) to single-cell lysosomal pH gradients (4.5–6.2)." (PMID 40871015, 2025). "BRCA1 and BRCA2 genes were discovered in 1994 and 1995, respectively, that their encoding proteins involved in tumor suppression, regulating cell replication, DNA damage repair, and normal cell growth in the human body." (PMID 40104509, 2025). "Unintriguingly, CellChat analysis underscored more frequent cellular interactions occurred in the BRCA1-MT group, marked by an abundance of non-tumor cells." (PMID 40904511, 2025). "After PARPi treatment for 6 days, the tumor organoids from the xenograft models of the BRCA2 hypermethylated patient showed a decline in tumor cell nuclei, in contrast to the organoids with BRCA wildtype, but similar to the BRCA1 mutated organoids." (PMID 39392573, 2025). "For example, during PARP inhibitor treatment, increased DNA methylation in the BRCA1 promoter region can lead to its downregulation, allowing tumor cells to regain DNA repair ability." (PMID 40395324, 2025). "The tumor suppressor PALB2 functions with the BRCA1 and BRCA2 proteins to maintain genomic integrity by homologous recombination." (PMID 39745016, 2025). "Impaired HR through mutations in BRCA1, BRCA2, PALB2, or potentially other mechanisms, can increase the rate of point mutations and random insertions and deletions, promoting tumor neoantigen formation and presentation, and cytotoxic T-cell infiltration." (PMID 40426860, 2025). "For example, BRCA1 is highly conserved between humans and dogs, suggesting a shared mechanism of tumor suppression and DNA repair, as evidenced by the crucial RING and BRCT domains." (PMID 40004231, 2025). "Responders were enriched for MMR-d, BRCA1/2 loss, high TIL density, CDK12 loss, ATM or CHD1 alterations, underscoring the predictive value of a broad tumor-based immunogenic signature." (PMID 40806607, 2025). "One type is primary resistance: tumor cells have inherent resistance characteristics before treatment, commonly found in tumors with wild type DNA repair genes (such as BRCA1/2) or metabolic enzyme defects." (PMID 41293424, 2025). "The data revealed that the expression of Smyd3 and Esr1 at the mRNA level was increased in MTV, MTP12, and tumor tissues compared with age-matched Brca1-WT controls." (PMID 40157910, 2025). "Experimental evidence has further demonstrated that BRCA1/2‐mutant tumour cells are approximately 1000 times more sensitive to PARP inhibitors than wild‐type BRCA cells." (PMID 40859871, 2025). "It has been proposed that PVs in exon 10 lead to a decrease in the tumor suppressor activity of BRCA1, by reducing DNA repair activity, and consequently to an increase in unrepaired mutations and chromosomal abnormalities." (PMID 41440233, 2025). "Since the wild-type BRCA allele is typically lost during tumor development, BRCA1 and BRCA2 are classified as classic tumor suppressor genes." (PMID 41373813, 2025).
tumor (continued). "In this study, we discovered that METTL1 boosts BRCA1 expression through m7G modification, thereby facilitating cell proliferation and tumor growth in HGSOC." (PMID 41430564, 2025). "BRCA1 and 2 are expressed ubiquitously and are recognized for their tumor suppressor role, with somewhat perplexing tissue specificity (principaly breast and ovarian)." (PMID 41373491, 2025). "When the BRCA1 or BRCA2 function is lost, either by inherited mutations or through somatic alterations in tumor cells, the result is impaired DNA repair." (PMID 40870889, 2025). "BRCA1/2 are crucial tumor suppressor genes that mediate DNA repair through homologous recombination, and their loss leads to a diminished capacity for DNA repair, rendering these tumors highly sensitive to DNA-damaging agents." (PMID 41077566, 2025). "It was discovered in 1996, in an effort to elucidate the biological function of the BRCA1 protein, and it is considered a putative tumor suppressor that can form stable heterodimers with BRCA1." (PMID 41301857, 2025). "BRCA1 carriers more frequently develop triple-negative breast cancers, while BRCA2 mutation carriers exhibit a broader tumor spectrum, including increased risks of prostate, male breast, and pancreatic cancer." (PMID 40243654, 2025). "The BRCA1 is a known tumor suppressor gene that plays an important role in protecting genomic stability." (PMID 40259965, 2025). "The doxycycline-induced knockdown of OFD1 and downregulation of BRCA1 in tumor tissues were validated by western blot analysis." (PMID 40764600, 2025). "In BRCA1/2-deficient tumors, CD4+/CD8+T cells, endothelial cells, and functional stromal cells show strengthened spatial interactions with tumor epithelial cells, and CD8+T cells are mainly distributed near the tumor cells." (PMID 40830526, 2025). "Most worryingly, the founder Jewish BRCA1/2 PVs identified on testing of tumours in an Israeli study were all assigned to the somatic group despite these being almost certain to be germline." (PMID 40046829, 2025). "In a previous study, we identified 169 candidate genes that trigger tumor formation by integrating the SB system into the Cre-LoxP-mediated Brca1 mammary gland-specific knockout (Brca1co/co;Wap-Cre;SB and Brca1co/co;MMTY-Cre;SB) mouse model." (PMID 41318657, 2025). "Immunohistochemistry (IHC) was performed on formalin-fixed paraffin-embedded (FFPE) tumor tissue samples from these patients to assess BRCA1 expression." (PMID 40495194, 2025). "The BRCA1 and BRCA2 genes [BRCA1/2] are tumor suppressor genes that code for proteins involved in double-strand DNA damage repair." (PMID 40427184, 2025). "The BARD1 and BRCA1 proteins form a heterodimer with multiple tumor-suppressing functions related to DNA repair and apoptosis." (PMID 40869938, 2025). "Comprehensive genomic profile results demonstrated a higher tumor mutational burden (TMB) (< 0.001) and lower tumor BRCA1/2 expression (< 0.001) in patients with mutations in the AKT pathway." (PMID 39466567, 2025). "For example, hypermethylation of tumor suppressor genes such as PTEN and MLH1 in endometrial cancer inactivates regulatory pathways, while in ovarian cancer, abnormal BRCA1 methylation impairs DNA repair, contributing to tumor progression." (PMID 40277318, 2025). "Then, we implanted either WT B477 cells or Brca1 mutant G600 cells into the fat pads of these mice at the day when we detected vaginal plug was detected (0.5 day of pregnancy, P0.5) and monitored tumor growth." (PMID 40157910, 2025).
tumor (continued). "In BRCA1-deficient OC cells, PARP inhibitors (PARPi) can induce ferroptosis, and their combination with GPX4 inhibitors exhibits significant synergistic anti-tumor effects." (PMID 40539051, 2025). "As a multifunctional gene, BRCA1 is integral to the cellular DNA damage response and repair pathways, underscoring its importance in tumor suppression." (PMID 39997609, 2025). "BARD1 (BRCA1-associated RING domain protein 1) on chromosome 2q34-q35 interacts with BRCA1 to participate in DNA damage repair and tumor suppression." (PMID 41395620, 2025). "Next, we evaluated the relationship between immunotherapeutic response and BRCA1-related classification systems including BRCA1 mutation and BRCA1-like via the TIDE (Tumor Immune Dysfunction and Exclusion) algorithm." (PMID 40904511, 2025). "Subsequently, we conducted Gene Ontology (GO) enrichment analysis on the gene set comprising the BRCA1 regulon in tumor cells." (PMID 41354912, 2025). "The complexity of the tumour methylation level analysis, which is reliant on accurate tumour purity and copy number estimation, is a known limitation of BRCA1 and RAD51C methylation characterisation studies." (PMID 39055334, 2024). "Patients with loss-of-function mutations in BRCA1 or BRCA2 can present with a more aggressive BC phenotype, including triple-negative BC (TNBC), higher tumour grade, and higher oncotype risk of recurrence score." (PMID 39215191, 2024). "Panel sequencing of HRR-related genes additionally identified 1 tumor with a likely BRCA1 PV with gsLOH, 2 with BRCA2 PVs with gsLOH, and 1 tumor with a PV in PALB2 without gsLOH." (PMID 38648056, 2024). "In particular, most BRCA1-related MBCs are grade 3, HER2-negative (HER2-) tumours with high proliferative activity, whereas BRCA2-associated MBCs are high-grade, HER2-positive (HER2+) tumours and show absence of progesterone receptor (PR) expression." (PMID 38974244, 2024). "Bioinformatic analysis showed that the tumorigenesis was predominantly driven by the BRCA1 variant with LOH, as indicated by the HRD-related mutational signatures in the tumor." (PMID 38063999, 2024). "Beyond BRCA1/2, performing tumour HRR gene testing in addition to germline testing increases initial costs but also increases the detection of gene mutations and can allow more patients to be eligible for and benefit from PARPis." (PMID 39796639, 2024). "Tumor cells that were are refractory to PARPi (abbreviated as “PARPi-Res” in the figure) from both PARPi-treated Brca1-def and Bard1-def tumors were then isolated, re-injected into the mammary glands of new B6/129F1 recipient mice and treated." (PMID 38956205, 2024). "Each of these agents has been designed to exploit the concept of synthetic lethality in tumours with deficiencies in HRR, particularly those with BRCA1/2 mutations." (PMID 39360040, 2024). "Tumor BRCA1-PM was present in 146 (36.5%) out of the 400 patients with available methylation status." (PMID 38191387, 2024). "Follow-up studies examining the frequency of low tumour BRCA1 or RAD51C methylation in the chemo-naïve setting will be critical for understanding early treatment resistance in OV and BC." (PMID 39055334, 2024). "In particular, BRCA1 promoter is methylated in different tumor types including breast (up to 20%) and ovarian (up to 19%) sporadic cancers." (PMID 38577595, 2024). "The frequency distribution of PLP variants in the gene structures, including UTR, intron, and exon, was similar among healthy individuals and tumor patients for both BRCA1 and BRCA2." (PMID 38566028, 2024). "BRCA1 PVs have been shown to alter the TME by directly enhancing epithelial-to-mesenchymal transition (EMT) in tumour cells." (PMID 39682099, 2024).
tumor (continued). "Its interaction with BRCA1 is regulated by its N-terminal domain, playing a role in enhancing its DNA repair capabilities and tumor suppressor functions." (PMID 39390525, 2024). "BRCA1 PVs also influence the tumour microenvironment through its effects on surrounding stromal cells." (PMID 39682099, 2024). "In contrast, and surprisingly, we found that tumours with CRS3 were less likely to have a germline BRCA1 PV than those with germline BRCA1/2 wild type." (PMID 39550490, 2024). "ATR inhibitors block this BRCA1-independent function, making tumor cells sensitive to reactivation of PARP inhibition." (PMID 39334297, 2024). "What is evident from our study is that a large number of tumours with CRS3 have germline BRCA1/2 wild type." (PMID 39550490, 2024). "M. oleifera leaves extract/Caffeine loaded chitosan nanoparticles downregulated the expression of BRCA1 & 2 in tumor tissue." (PMID 39103402, 2024). "‘s study demonstrates that inhibiting or depleting BET proteins affects the transcription of BRCA1 and makes various tumor cells sensitive to PARP inhibitors." (PMID 39156700, 2024). "In fact, BRCA1 and BRCA2 mutated cells are more responsive to anti-tumor treatments that induce the accumulation of damage to the DNA double strand, the so-called PARP-inhibitor." (PMID 39335746, 2024). "Consistently, the expression of CtIP in Gata3+/− tumor cells was lower than in Gata3+/+;Brca1+/+ cells." (PMID 38627785, 2024). "This also suggests that both WWOX and BRCA1 play crucial roles in maintaining the normal function of cellular processes, such as DNA integrity, that prevent tumor development." (PMID 38499540, 2024). "The SBS26-positive patients displayed a BRCA1/2 wildtype for the germline and tumor (n = 2), a germline wild type (n = 1), or had a germline BRCA2 mutation (n = 1) and were treated with niraparib (n = 3) or olaparib (n = 1)." (PMID 38927686, 2024). "Recent discoveries implicate BRCA1, a known tumor suppressor, as essential for regulating the levels of S100A8 and S100A9 in the body." (PMID 39057065, 2024). "Tumor grade was intermediate-high (grade 2–3) in all patients, with more high-grade tumors among BRCA1/2 carriers (88% vs. 68%, P = 0.060)." (PMID 38365640, 2024). "We then further examined the 47 HGSC-like OCSs to see if they had tumor or germline BRCA1/2 testing performed." (PMID 39220645, 2024). "Increased HOTAIR expression induces epigenetic changes on both ESR1 and BRCA1 genes, promoting increased expression of ER-alpha, strengthening DNA stabilization and tumor regression." (PMID 39329990, 2024). "A multicentre, individual patient data meta-analysis performed by The HGSC CRS Collaborative Network did report a positive associated between tumours with CRS3 and a germline BRCA1/2 PV (P = 0.027)." (PMID 39550490, 2024). "BRCA1, a tumor suppressor, is involved in multiple biological processes, including transcription, cell cycle progression, and DNA damage repair." (PMID 39125994, 2024). "Wild-type BARD1 is known to function as a tumor suppressor through pathways that are BRCA1-dependent and independent." (PMID 39233942, 2024). "To understand the effects of combination therapy in tumor microenvironment, we analyzed the immune landscape of Brca1-proficient tumors using cytometry by time-of-flight (CyTOF)." (PMID 38622115, 2024). "HR deficiency is often driven by loss of BRCA1, BRCA2 or PALB2 function in tumor cells, which is the result of inactivating mutations and LOH." (PMID 38589664, 2024). "Among the 66 patients with tumor BRCA1-PM and ≥ 50% sTILs, we observed excellent 15-year OS (97.0%; 95% CI, 92.9–100%)." (PMID 38191387, 2024).
tumor (continued). "We used this method to evaluate the presence in FFPE samples of BRCA1 foci in proliferating (geminin positive) tumor cells because HR is restricted in cells in the S-phase, without the need to induce external DNA damage." (PMID 38989145, 2024). "We showed a relatively low incidence of second primary tumors in gBRCA1wt patients, especially in tumor BRCA1-PM patients." (PMID 38191387, 2024). "It is crucial to understand the pathogenetic mechanisms underlying the mutations in the BRCA1 and BRCA2 genes and how these are qualitatively and quantitatively linked to the risk of developing pre-tumour lesions like STIC and gynaecological cancers." (PMID 39594243, 2024). "Actually, BRCA1 can indeed be restored to normal expression levels by demethylation when detected in clinical tumor recurrence samples." (PMID 39318358, 2024). "Of the 502 BRCA1/2 tumor analyses performed in our cohort, a total of 244 analyses (48.6%) were performed using the hybrid capture technique and 133 analyses (26.5%) using the PCR-based technique." (PMID 38730634, 2024). "Mutations affecting other components of the HR machinery, such as BRCA1 or BRCA2, increase the rate of genetic mutations, leading to substantially increased tumor risk." (PMID 38530355, 2024). "In BRCA1 and BRCA2 mutated tumor cells, the HRD activity was compromised; therefore, the collapsed replication forks are unable to be repaired, and cell death occurs." (PMID 39335746, 2024). "Arguably the most important effect BRCA1/2 PVs have on the tumour microenvironment is its influence on the immune response, as the association between the tumour microenvironment and inflammation is frequently complex and bidirectional." (PMID 39682099, 2024). "Over the last decade, researchers have thoroughly investigated the tumor suppressor genes BRCA1 and BRCA2." (PMID 38903278, 2024). "Although PARPi treatment suppressed tumor growth for several weeks, tumors began to progress and eventually became refractory to the treatment in all treated Brca1-def mice." (PMID 38956205, 2024). "BC prognosis is traditionally based on tumor, node, and metastasis (TNM) staging, molecular subtype, and BRCA1 gene family mutation." (PMID 38832155, 2024). "AHR also dysregulates BRCA1 expression, a crucial tumour suppressor in HGSOC and is additionally correlated with an unfavourable prognosis in OC." (PMID 38361045, 2024). "As the majority of tumor cells depend on the G2/M checkpoint for DNA repair, the increase of BRCA1 and the elevated percentages of CaSR-overexpressing cells in the LUAD cell lines in G2/M phase imply that these cells possess a more adequate DNA repair process." (PMID 39113697, 2024). "PARP inhibitors enable synthetic lethality in tumour cells with homologous recombination deficiency (HRD), especially those with mutated BRCA1/2 (BRCAm)." (PMID 38755585, 2024). "In this study, we identified a subset of primary OV and TNBC cases exhibiting low tumour level methylation in BRCA1." (PMID 39055334, 2024). "However, BRCA1-deficient cancer cells can influence the metabolism of surrounding fibroblasts by producing large amounts of hydrogen peroxide, which activates nuclear factor-kappa B (NF-κB) signaling to induce mitochondrial autophagy in tumor matrix cells, thereby promoting tumor growth." (PMID 39763653, 2024). "BRCA1 and RAD51C promoter methylation also causes HRD but often incompatible with BRCA mutations in tumor tissue." (PMID 39334297, 2024). "BRCA1 is a tumour suppressor gene involved in the repair of DNA double-strand break repair through homologous recombination." (PMID 39021548, 2024).